SNORA11C (small nucleolar RNA, H/ACA box 11C)
Gene: Small nucleolar RNA gene on chromosome X (47,388,649 to 47,388,777, forward strand). Ensembl gene ENSG00000221459.
Gene Ontology:
Biological process: RNA processing
Cellular component: nucleolus
Homologues: Orthologues: chimpanzee SNORA11C (100% identical), macaque SNORA11C (95% identical). Paralogues in human: SNORA11B (89% identical), SNORA11D (88% identical), SNORA11E (88% identical), SNORA11F (87% identical), SNORA11 (84% identical), SNORA11G (75% identical).